CD4 (CD4 molecule)
Diseases named in the same sentence as CD4 in open-access papers (continued):
Sharing a sentence is not in itself a finding about the gene and the disease.
tumor (continued). "Despite the delayed tumor growth, we did not observe a statistically significant difference in CD4+ and CD8+ T cell infiltration." (PMID 38250876, 2024). "In general, CD4+ T helper 1 (Th1) cells, CD8+ cytotoxic T cells, NK cells, and M1 macrophages have a protective activity against tumor development, whereas Treg, CD4+ T cells (Th2), and M2 macrophages can promote tumor growth." (PMID 38793599, 2024). "Importantly, anti-IL-33 monoclonal antibody therapy increase the percentage of CD4+IFNγ+ T cells and decreased CD4+ and CD8+ T cells secreting IL-4 in tumour-draining lymph nodes." (PMID 38662248, 2024). "In our reference- and methylation-based deconvolution of gcGB versus non-gcGB tumor bulk we found lower proportions of CD4+ T cells in the gcGB microenvironment." (PMID 39663543, 2024). "We therefore depleted CD4 + T cells, CD8 + T cells, or natural killer (NK) cells to determine which population might be responsible for tumor elimination in mice bearing TC-1 tumors." (PMID 38459592, 2024). "CD4+ cells are essential for maintaining and sustaining CD8+ TIL-mediated anti-tumor responses." (PMID 38779258, 2024). "As a newly identified checkpoint, T cell immunoreceptor with immunoglobulin and tyrosine-based inhibitory motif (ITIM) domain (TIGIT) is highly expressed on CD4+ T cells, CD8+ T cells, natural killer (NK) cells, regulatory T cells (Tregs), and tumor-infiltrating lymphocytes (TILs)." (PMID 38229100, 2024). "Furthermore, Isoliquiritigenin treatment increased the presence of CD4+ and CD8+ T cells within tumor tissues, suggesting that Isoliquiritigenin have the potential to trigger protective anti-tumor immune responses." (PMID 39650709, 2024). "Therefore, CD4 and CD8 T cells were essential to the reduced tumour burden, slower tumour progression, and prolonged survival observed in Fgl2−/− mice." (PMID 38191799, 2024). "Taken together, these results indicate that tumor-derived GLI1 plays an important role in sustaining expansion and recruitment of PMN-MDSCs, in promoting their immunosuppressive phenotype, and in suppressing CD8 + and CD4 + T cell function." (PMID 39090759, 2024). "Moreover, it increases the presence of CD4+ IFN-γ+ T cells and CD8+ IFN-γ+ T cells within the spleen and tumor microenvironment." (PMID 38891683, 2024). "CD4, CD25, and FOXP3 co‐labeled T cell phenotypes were used to assess tumor‐infiltrating Tregs." (PMID 39264227, 2024). "While this observation is based on a low sample size, it suggests that the presence of CD8 T cells without CD4 T cells, B cells, and the expression of key T cell phenotypic markers, is not sufficient to achieve an anti-tumor response." (PMID 39190534, 2024). "Furthermore, mIF results indicated that the patients with ITGAL-high expression tend had significantly higher CD8+ T cells, CD68+ macrophages, CD4+ T cells, and CD20+ B cells infiltration in their tumor tissues." (PMID 38646528, 2024). "Their findings were followed by a report that, in a study, immunogenic tumor neo-antigens induced a CD4+T cell response but not the expected CD8+T cell response." (PMID 39000005, 2024). "Moreover, both CD8 T cells in the tumor-draining lymph node (TDLN) and CD4 T cells in the tumor and TDLN, showed an increase in IFN-γ expression in CD244fl/flLysMcre mice compared to CD244fl/fl mice." (PMID 38424542, 2024). "TGF-β prevents immature T cells from differentiating into Th1 cells, promoting Foxp3 to encourage the differentiation of naïve CD4+ T cells into Treg cells and regulating TGF-β signaling to mediate the anti-tumor immune function of Treg inhibiting CD8+ T cells in the TME." (PMID 39372416, 2024). "In addition, PRKAA2 facilitates immune escape of tumor cells by promoting CD8+ T-cell exhaustion and the formation of CD4+ Treg cells by reshaping the interaction between malignant cells and T cells and driving dynamic changes in T cells in the TME." (PMID 38424484, 2024).
tumor (continued). "NIR light triggered photosensitizer-induced PTT combined with oxaliplatin prodrug-induced CT to kill tumor cells, while activating the ICD effect to enhance the antitumor response, which significantly increased the ratio of CD8+ T cells and CD4+ T cells in TME." (PMID 38840653, 2024). "We identified ligand-receptor pairs involved in the interactions between CD4+ T cells and macrophages, specifically in the tumor tissues of non-responsive patients." (PMID 38948071, 2024). "CD4 + T cells can target tumor cells directly through cytolytic mechanisms or indirectly by modulating the TME and mediating CD8 + cytotoxic T lymphocytes to kill tumor cells." (PMID 38802480, 2024). "Given that we detected significantly more circulating CD8+ than CD4+ T cells, it is likely that systemic TLR9 stimulation boosts global immunity, which consequently may act on the tumor." (PMID 38201300, 2024). "Considering that CD4+ T cells play a key role in tumor immunity and that the inhibition of TCR signaling may affect anti-tumor activity in CD4+ T cells, we explored whether PTPRJ could serve as a therapeutic target for enhanced peripheral immunity." (PMID 38735538, 2024). "Moreover, to investigate the potential interactions between FABP4+C1q+ macrophages and other immune cells in tumor microenvirment (TME), IHC staining was performed for CD4+ T cells, CD8+ T cells, CD20+ B cells." (PMID 39353883, 2024). "Furthermore, the activation level of tumor‐infiltrated T cells, evaluated by the CD69 expression level, was decreased in mice with anti‐CD4 treatment in comparison with IgG treatment." (PMID 39225354, 2024). "Therefore, we assessed the percentage of tumor-infiltrating lymphocytes (TILs) using CD3, CD4, CD8, and PD-L1 expression within the tumor microenvironment by immunohistochemistry." (PMID 39596374, 2024). "The delivery of tumor antigens derived from the C6 cell membrane efficiently elicited the antitumor immune responses, leading to a significant increase in the expression of CD8 and CD4 at tumor sites and spleen following in vivo injection of DNS-[C6&DC]m." (PMID 38549161, 2024). "In contrast, in B16-OVA melanoma tumor bearing model, c-Rel rather than Rel-A, was essential for the control of tumor growth and enhancement of anti-PD-1 treatment by impacting CD4+ Tconv." (PMID 39493763, 2024). "Previous studies have shown that the distance from immune cells to tumor nests is a critical factor affecting prognosis Moreover, the separation among CD20+ B cells, CD4+ T cells, and CD8+ T cells leads to distinguished spatial immune architectures affecting the functional state of immune cells." (PMID 38887237, 2024). "In the tumor tissues, OMV-PP resulted in the increased infiltration of CD4+ and CD8+ T cells." (PMID 38166929, 2024). "Although the difference in the proportion of CD4+ T cells was not statistically significant, CR705Parp7KO tumours with the highest relative CD8+ T cell infiltration also had the lowest relative CD4+ T cell infiltration." (PMID 39867896, 2024). "Strikingly, only the loss of tumor NLRC4, but not stromal NLRC4, was associated with poor immune infiltration (mainly DCs and CD4+ and CD8+ T cells) and accurately predicted progression to metastatic stage IV and decrease in overall survival." (PMID 38652550, 2024). "The low expression of SMARCA4 might enhance the anti‐tumor immune response by regulating the TME, which could increase the infiltration of anti‐tumor immune cells, such as CD4+ T cells and CD8+ T cells." (PMID 39322625, 2024). "There was no change in the tumor-free survival in the mice when they underwent CD4 depletion itself, according to the groups that were treated with or without DMBA or with and without SQV." (PMID 39339897, 2024). "Whereas in the absence of tumor cells, irradiation of CD4+ T cells with 90Y-NM600 significantly reduced their viability." (PMID 39355211, 2024).
tumor (continued). "Additionally, a strong link between sPD-L1 and CD4+CD25+Foxp3+ regulatory T cells in BCR cases was observed, indicating sPD-L1’s systemic impact on tumor progression." (PMID 39055716, 2024). "Platelets from NSCLC patients were found to express PD-L1, and platelet PD-L1 possesses the ability to inhibit CD4 and CD8 T cells, confirming their important roles in tumor immune evasion and overcoming the limitations of histological quantification of heterogeneous intratumoral PD-L1 expression." (PMID 39219215, 2024). "Moreover, the IHC imaging revealed OMV-PP increased infiltration levels of CD4+ and CD8+ T cells into the tumor tissues." (PMID 38166929, 2024). "Previously, we investigated the effect of IL-2 on the activation of cytotoxic lymphocytes and for the first time showed that CD4+ and CD8+ cytotoxic T lymphocytes are generated under the action of this cytokine, killing HLA-negative tumor cells via FasL-Fas interaction." (PMID 38203798, 2024). "This TCR alongside three other KRAS G12V–reactive TCRs derived from peripheral blood T cells of two healthy donors underwent in vitro testing for specificity, cross-reactivity, functional avidity, function in CD4+ T cells (CD8 coreceptor dependency), and tumor cell-line recognition." (PMID 39484723, 2024). "However, in specific settings the inclusion of a universal helper antigen in a vaccine can in fact reduce anti-tumor CD8+ T cell immunity, most likely by interfering with vaccine-induced tumor-specific CD4+ T cell responses." (PMID 39040850, 2024). "Indeed, we were able to demonstrate the existence of functional CD4+ and CD8+ tumor-specific T cells and found a greater number of these cells when tumors were injected with NDV-αCTLA-4 or NDV-sPD-1 compared to the PBS- and NDV-GFP-treated controls." (PMID 38328418, 2024). "Lymphocytes - including CD8+ cytotoxic and CD4+ helper T cells, natural killer (NK) and NKT cells – together with dendritic cells (DC) and pro-inflammatory macrophages (M1-like) have the power to induce an anti-tumoral response leading to tumor cell death." (PMID 39703517, 2024). "Interestingly, CD4 and CD8 T cells from healthy samples (hTcells) formed a distinct cluster, adjacent to CD4 (tCD4) and CD8 T cells (tCD8) from tumor samples." (PMID 39516494, 2024). "We examined CD4, CD8, CD68 and CD163 cells for analysis of the tumor microenvironment in both intratumoral and stromal compartments, as well as the overall number of tumor microenvironment cells." (PMID 39123373, 2024). "Based on target cell expansion (CD8+ or CD4+ effector memory T cells) in tumor and peripheral blood (data not shown), 0.01 mg/kg of PD1/IL15 TaCk was identified as mPAD in a humanized (hCD34+ engrafted in NSG) mouse model." (PMID 38887559, 2024). "In addition, a high NLR reflects decreased lymphocyte-mediated immunity (with an altered CD4+ helper/CD8+ suppressor ratio) and increased production of inflammatory agents such as vascular endothelial growth factor (VEGF), which promote tumor growth." (PMID 39596977, 2024). "To examined whether activated T cells play a role in the anti-tumor effects of CD276 cKO, we block T lymphocytes following MB49 subcutaneous implantation by injection of anti-CD4 or anti-CD8 antibodies." (PMID 38561369, 2024). "In this study, we found that the CTLA4, CD68, and CD4 genes were closely related to THC and CMS1 CRC; therefore, this suggested that CHCs and THCs may act as a new marker of immunotherapies in tumor treatments in the future." (PMID 39499374, 2024). "Contrastingly, the C57BL/6 mice showed a significant reduction in tumor volume in mice treated with the FAP CAR, and this also correlated with an increased number of host CD8+ T cells within the tumor and higher numbers of TNF-α-producing CD4+ T cells." (PMID 39335157, 2024). "Given that these genes could potentially influence the tumor purity of DLBCL, we then analyzed the relationship between them and CD68 + macrophages, CD4 + T cells, and CD8 + T cells." (PMID 38980810, 2024).
tumor (continued). "However, our findings also showed that this approach enhances the infiltration of CD4+ and CD8+ T cells in tumor tissue." (PMID 38616190, 2024). "Anti-CTLA4 works at the T cell–APC immune synapse by promoting the unopposed interaction of B7 costimulatory ligands with CD28, thereby enhancing the activation of CD4+ and CD8+ T cells and rebalancing the regulatory compartments within the tumor microenvironment (TME)." (PMID 39204053, 2024). "We also assessed tumor infiltrating CD8+ and CD4+ T cells from MC38 tumors." (PMID 38942798, 2024). "Gene expression analysis of tumor scRNAseq data demonstrated a significant upregulation in pathways related to T cell activation and differentiation, cell adhesion, and cytokine production post-sotigalimab for both CD8+ and CD4+ T cells." (PMID 38181044, 2024). "The study revealed that the frequency of TIM-3(+) CD4 T cells was significantly higher in tumor tissues than in non-tumor invasive lymphocytes from peripheral blood." (PMID 39206199, 2024). "Tumor-derived GLI1 sustains expansion and invasion of PMN-MDSCs in vitro, and promotes their immunosuppressive activity on T cells, inhibiting their effector capability, as demonstrated by the reduced production of IFNγ by CD4 + and CD8 + T cells." (PMID 39090759, 2024). "Antibody depletion of CD4/CD8 T cells does not fully prevent Salmonella-mediated reduction in tumour volume, and adoptive transfer of anti-tumour, STm-generated T cells show no therapeutic capacity." (PMID 39558103, 2024). "Consistently, transfer of WT LCMV-specific memory CD4+ T cells potentiated the anti-tumor function of NDV-GP administration in recipients without LCMV Armstrong exposure." (PMID 38609488, 2024). "Furthermore, cell death through CD8+ cytotoxic T cells and natural killer (NK) cells, as well as tumor cell senescence induced by CD4+ Th1 cells that produce IFN-γ and TNF-α, inhibits tumor growth." (PMID 38297164, 2024). "As two subpopulations of CD3 + T lymphocytes, CD8 + T cells exert anti-tumor immune effects through antigen-specific and antigen-nonspecific mechanisms while CD4 + T cells contributing to the activation of CD8 T cells." (PMID 38395827, 2024). "Studies have observed that treatments increasing CD4+ T cell infiltration in TNBC can amplify the anti-tumor immune response, particularly when CD4+ cells foster CD8+ T cell proliferation, differentiation, and retention within the tumor microenvironment." (PMID 39769460, 2024). "Finally, the DCs present antigens to the T cells, which produce a large number of tumor antigen-specific CD4+ T cells and CD8+ T cells that specifically recognize and kill tumor cells." (PMID 38534538, 2024). "It’s interesting to note that the expression of major histocompatibility complex-II (MHC-II) molecules, which are involved in antigen presentation, was not necessary for the tumor cells to express CD4+ T cells’ anti-tumor function." (PMID 38391974, 2024). "The unexpected absence of CD69 and CD25 in C002-induced CD4(+) T cells raises questions about the optimal time for conducting immunophenotyping of tumor infiltrates to capture the nuanced changes in T cell activation." (PMID 38895115, 2024). "IL-33 also has a role in the anti-tumour response to melanoma by not only increasing the secretion of INFγ and granzyme B from CD8+ T and NK cells as well as proliferation of CD4+ T cells but also reducing the differentiation of PMN-MDSCs from bone marrow cells." (PMID 38893071, 2024). "Based on the results of three algorithms, TIMER, MCPCOUNTER and CIBERSORT, we found a significant correlation between the expression level of RFC4 in tumours such as KIRC, LUAD and LIHC and the infiltration degree of CD4 + T cells, CD8 + T cells, B cells, macrophages and dendritic cells." (PMID 39031628, 2024). "Interestingly, higher expression of these genes is related to higher CD4+, CD8+, and FOXP3+ T cells as well as with higher CD163 macrophages tumor infiltration." (PMID 38790160, 2024).
tumor (continued). "CD4+ T cells can present tumor antigen epitopes; promote the activation of CD8+ T cells and the effector and memory functions of CTLs; and secrete IFN-γ, IL-2, and TNF-α to improve CTL activity and assist in killing tumor cells." (PMID 39408814, 2024). "Increased APCs, CD4+, CD8+, and interferon gamma indicate increased tumor vaccine effectiveness." (PMID 39682188, 2024). "Animals treated with ADU-S100 + anti-ISG15 had a significant increase in the frequency of tumor infiltrating CD62L+CD44+ central memory CD8+ and CD4+ T cells compared to those treated with ADU-S100 alone, as well as an increase in CD44+CD62L- effector CD4+ TIL." (PMID 38312842, 2024). "Conversely, we found little to no expression of CD4, CD8, or NK1.1 on cells expressing CFSE, confirming that mostly tumour‐associated macrophages (CD11b+ F4/80+, 90% of CFSE+ cells) take up EVs in vivo." (PMID 39330930, 2024). "Furthermore, STAT6D419 mutant tumor cells secrete more of the chemokine CCL17 upon IL-4 stimulation, and we are the first to provide evidence that this leads to increased CD4+ T-cell infiltration in rrDLBCL patient tumor biopsies." (PMID 38285120, 2024). "Furthermore, in the CD47highest group, a significant increase in CD4+ cell (threefold, p = 0.032) and CD8+ cell (2.4-fold, p = 0.011) tumor infiltration was observed after NACT." (PMID 39138571, 2024). "Previous research has showed that expression of STK11 was positively correlated with intertumoral infiltration of cluster of differentiation CD3+, CD4+, and CD8+ cells, demonstrating patients with high levels of STK11 would have better immune conditions for tumor control." (PMID 38736875, 2024). "Notably, CD4 + and CD8 + neoantigen-reactive tumor-infiltrating lymphocytes (TILs) exhibited distinct signatures across different stages." (PMID 38645221, 2024). "In addition, in GBM, CD4+ T and CD8+ T cells are frequently exhausted and dysfunctional and, therefore, ineffective at tumor control." (PMID 39594814, 2024). "The prognostic value of CD3, CD4, and CD8 will also be evaluated based on tumor stage." (PMID 38926643, 2024). "Additionally, IFN-γ-dependent anti-angiogenesis has been reported as a mechanism in tumor rejection by CD8 and CD4 effector T cells." (PMID 39629126, 2024). "We showed that the anti-tumor effects of anti-CTLA-4 therapy were dependent on CD4+ T cells, but not CD8+ T cells in this model." (PMID 39106430, 2024). "Statistical analysis further indicated a significantly higher proportion of these CD4+ T cell subpopulations in the tumor samples than in the adjacent nontumor samples (p < 0.05)." (PMID 38292868, 2024). "Moreover, positive PD-L1 CPS was more often detected in patients with high CD4+ T cells and high CD8+T cells infiltration level in tumour tissue (p = 0.021 and p = 0.048)." (PMID 38541208, 2024). "Consistently, IL-33−/− tumor-bearing mice had lower frequencies of tumor-infiltrating CD4+ T cells and CD8+ T cells, while no consistent alterations were observed in the overall populations of CD4+ T cells and CD8+ T cells." (PMID 38430390, 2024). "-Induction of TNF-α and IL-12p70 levels (in vitro).-Increased body weights of mice (decreased when NPs administered with adriamycin).-Increased serum TNF-α levels and CD4+/CD8+ lymphocyte ratios and decreased serum IL-10 levels (in vivo).-Increased tumor inhibition rate and decreased tumor growth." (PMID 39591094, 2024). "The neighborhoods differed slightly in their composition of cell types, with the Treg neighborhood comprising a higher proportion of DCs and CD4+ T cells, whereas the no Treg neighborhood contained a higher tumor and type 2 macrophage portion." (PMID 39485838, 2024).